IRGC (immunity related GTPase cinema)
Description:
GTPase required for sperm motility and therefore male fertility, via positive regulation of spermatozoa fibrous sheath formation.
Synonyms: IIGP5; IRGC1; CINEMA; IFGGE; R30953_1
Tractability: No criterion of Open Targets' tractability assessment is met for any kind of drug.
Gene: Protein-coding gene on chromosome 19 (43,716,076 to 43,720,021, forward strand). Ensembl gene ENSG00000124449.
Subcellular location: Cell projection, cilium, flagellum; Lipid droplet
Gene Ontology:
Molecular function: protein binding; GTP binding; GTPase activity
Biological process: positive regulation of flagellated sperm motility
Cellular component: lipid droplet; sperm flagellum; sperm mitochondrial sheath; membrane; motile cilium
Genetic constraint (gnomAD): Loss-of-function variants: 12 observed, 23.5 expected, observed/expected ratio (o/e) 0.51, 90% interval 0.33 to 0.83. The upper end of that interval is the gene's LOEUF score, 0.83, which puts it in group 3 of 6, group 1 being the genes least tolerant of losing a copy. Missense variants: 570 observed, 650.51 expected, observed/expected ratio (o/e) 0.88, 90% interval 0.82 to 0.94. Synonymous variants: 307 observed, 305.86 expected, observed/expected ratio (o/e) 1, 90% interval 0.91 to 1.1.
Homologues: Orthologues: chimpanzee IRGC (100% identical), macaque IRGC (97% identical), dog IRGC (92% identical), pig IRGC (91% identical), rat Irgc (90% identical), mouse Irgc (90% identical), guinea pig IRGC (90% identical), rabbit IRGC (61% identical), zebrafish irgf3 (35% identical), zebrafish irgf1 (35% identical), zebrafish si:ch73-171o20.1 (35% identical), zebrafish irgf2 (29% identical). Paralogues in human: IRGM (13% identical).
Diseases named in the same sentence as IRGC in open-access papers:
IRGC is named in the same sentence as 9 diseases in open-access papers, as found by Europe PMC text mining. Sharing a sentence is not in itself a finding about the gene and the disease. The quoted sentences say what the papers report.
asthma (1 paper, 2017). "Several other CpGs from the top 20 hits in the cross-sectional model of current asthma at 7.5 years, such as cg20673965 (IRGC) and cg19805160 (CCDC19), also demonstrated consistent direction of effect in both of the longitudinal models despite only weak evidence of an association." (PMID 29046734, 2017).
optic neuropathies (1 paper, 2023). "Taken together, our findings suggest that this iRGC model, which achieves both high yield and high purity, is suitable for investigating optic neuropathies, as well as being useful when searching for potential drugs for therapeutic treatment and/or disease prevention." (PMID 37540379, 2023).
infection (2 papers, 2005 to 2022). The state of being infected such as from the introduction of a foreign agent such as serum, vaccine, antigenic substance or organism. "Thus, IRGC is highly conserved in humans, dog and mouse, is not interferon or infection inducible, and is expressed constitively in mature testis." (PMID 16277747, 2005).
IRGC also shares sentences with these, for which no sentence is quoted: astrocytoma (1 paper); cancer (1); leiomyosarcoma (1); liposarcoma (1); male infertility (1); oligospermia (1).